PGLYRP2 (peptidoglycan recognition protein 2)
Description:
May play a scavenger role by digesting biologically active peptidoglycan (PGN) into biologically inactive fragments. Has no direct bacteriolytic activity.
Synonyms: PGRP-L; PGLYRPL; PGRPL; TAGL-like; tagL; tagL-alpha; tagl-beta; HMFT0141
Tractability: Antibody: its Gene Ontology location is reachable by antibodies, with high confidence; UniProt places it where antibodies can reach, with medium confidence; UniProt predicts a signal peptide or a membrane-spanning region.
Gene: Protein-coding gene on chromosome 19 (15,468,642 to 15,498,956, reverse strand). Ensembl gene ENSG00000161031.
Subcellular location: Secreted; Membrane
Subcellular location (Human Protein Atlas): Cell Junctions; Predicted to be secreted
Pathways (Reactome):
Immune System: Antimicrobial peptides
Gene Ontology:
Molecular function: molecular condensate scaffold activity; N-acetylmuramoyl-L-alanine amidase activity; peptidoglycan binding; peptidoglycan immune receptor activity; zinc ion binding
Biological process: defense response to Gram-positive bacterium; detection of bacterium; immune response; innate immune response; peptide amidation; peptidoglycan catabolic process
Cellular component: extracellular exosome; extracellular region; membrane
Genetic constraint (gnomAD): Loss-of-function variants: 37 observed, 42.89 expected, observed/expected ratio (o/e) 0.86, 90% interval 0.66 to 1.13. The upper end of that interval is the gene's LOEUF score, 1.13, which puts it in group 4 of 6, group 1 being the genes least tolerant of losing a copy. Missense variants: 713 observed, 722.4 expected, observed/expected ratio (o/e) 0.99, 90% interval 0.93 to 1.05. Synonymous variants: 289 observed, 311.68 expected, observed/expected ratio (o/e) 0.93, 90% interval 0.84 to 1.02.
Homologues: Orthologues: chimpanzee PGLYRP2 (96% identical), macaque PGLYRP2 (93% identical), dog PGLYRP2 (77% identical), pig PGLYRP2 (74% identical), rabbit PGLYRP2 (68% identical), mouse Pglyrp2 (67% identical), rat Pglyrp2 (66% identical), guinea pig PGLYRP2 (62% identical), tropical clawed frog pglyrp2 (32% identical), zebrafish pglyrp2 (31% identical), zebrafish pglyrp6 (31% identical), Drosophila melanogaster PGRP-LE (16% identical), and 9 more. Paralogues in human: PGLYRP3 (18% identical), PGLYRP4 (17% identical), PGLYRP1 (12% identical).
Diseases named in the same sentence as PGLYRP2 in open-access papers:
PGLYRP2 is named in the same sentence as 47 diseases in open-access papers, as found by Europe PMC text mining. Sharing a sentence is not in itself a finding about the gene and the disease. The quoted sentences say what the papers report.
Arthritis (6 papers, 2016 to 2021). Inflammation of a joint. "PGLYRP2 is indispensable in the induction of cytokines, chemokines and receptors in an arthritis model." (PMID 34461924, 2021). "In a mouse model of arthritis Pglyrp2 KO mice were partly protected against arthritis, and WT mice had higher levels of Il1b, Il6, and Tnf-α in the foot and a higher incidence of arthritis." (PMID 33833993, 2021). "NOD2 and PGLYRP-2 showed a synergistic effect in the development of local inflammation in an arthritis mice model since PGLYRP2−/− NOD2−/− mice were resistant to PGN or MDP induced arthritis." (PMID 31416116, 2019). "In the cross-regulation between PGRP and NOD, it has been reported that mouse PGLYRP-2 cooperates with NOD2 to activate pro-inflammatory genes in a PGN-induced arthritis model." (PMID 27991595, 2016). "Pglyrp2 protects mice against psoriasis-like skin inflammation, is required for the development of experimental arthritis, and exacerbates bacterial keratitis." (PMID 26727498, 2016). "This phenotype was already described for the PGLYRP2-KO mice in a MDP-induced arthritis model." (PMID 30837960, 2019). "However, the role of PGLYRP-2 in arthritis is unique because other mouse PGLYRPs, including PGLYRP-1, -3 and -4, do not have similar pro-inflammatory effects." (PMID 27991595, 2016).
COVID-19 (4 papers, 2022 to 2025). A disease caused by infection with severe acute respiratory syndrome coronavirus 2. "Other proteins that could potentially be employed in therapies against COVID-19 but that so far have not been associated with the disease are CD5L, VDBP, A1BG, C4BPA, PGLYRP2, SERPINC1, and APOH." (PMID 37371071, 2023). "Most of the chosen markers change in abundance between healthy and COVID-19-infected individuals, and further follow their respective trend with increasing treatment escalation level, such as peptides derived from the acute-phase proteins CRP and AHSG, or the innate-immune-response protein PGLYRP2." (PMID 35702332, 2022). "In addition, other proteins that could be employed in therapies against COVID-19 but that so far have not been associated with the disease are CD5L, VDBP, A1BG, C4BPA, PGLYRP2, SERPINC1, and APOH." (PMID 37371071, 2023).
psoriasis (4 papers, 2016 to 2024). An autoimmune condition characterized by red, well-delineated plaques with silvery scales that are usually on the extensor surfaces and scalp. "For example, PGLYRP2 protects against skin inflammation of psoriasis in mice by limiting the overactivation of Th17 cells and accelerating the accumulation of regulatory T cells at the inflammatory site." (PMID 34461924, 2021). "Pglyrp2 also protects mice against psoriasis-like skin inflammation by promoting regulatory T cells and limiting the Th17 responses." (PMID 33833993, 2021).
Anxiety (3 papers, 2022 to 2026). Intense feelings of nervousness, tension, or panic often arise in response to interpersonal stresses. "Another study showed that Pglyrp2 deficiency leads to major sex-dependent alterations in motor and anxiety-like behaviour, demonstrating that the effect of PGLYRP2 in the brain is modified by age, gender and neural circuitry." (PMID 41487016, 2026). "Moreover, Pglyrp2 knockout (KO) mice have been shown to display a sex-specific motor and behavioral phenotype at an older age with improved motor coordination and increased anxiety-like behavior in female mice." (PMID 38106542, 2023).
Parkinson disease (3 papers, 2019 to 2024). A progressive degenerative disorder of the central nervous system characterized by loss of dopamine producing neurons in the substantia nigra and the presence of Lewy bodies in the substantia nigra and locus coeruleus. "Moreover, PGLYRP2 gene polymorphisms are also associated with Parkinson’s disease." (PMID 38806963, 2024).
colitis (2 papers, 2019 to 2021). Inflammation of the colon. "This anti-inflammatory effect was probably linked to the influence of Pglyrp2 on the microbiota, because the susceptibility of Pglyrp2–/– mice to colitis could be transferred in stool to Pglyrp2+/+ germ-free mice." (PMID 33833993, 2021). "In a murine model of dextran sodium sulfate induced colitis Pglyrp2 showed anti-inflammatory properties by promoting normal gut flora and preventing induction of interferon-gamma." (PMID 33833993, 2021). "Interestingly, it was reported that PGLYRP-2−/− and PGLYRP-3−/− mice were highly sensitive to DSS-induced colitis than PGLYRP-1−/− and PGLYRP-4−/− mice, which had intermediate or low sensitivity, respectively." (PMID 31416116, 2019).
Crohn disease (2 papers, 2019 to 2024). A gastrointestinal disorder characterized by chronic inflammation involving all layers of the intestinal wall, noncaseating granulomas affecting the intestinal wall and regional lymph nodes, and transmural fibrosis. "PGLYRP2 polymorphisms in patients with ulcerative colitis and Crohn’s disease are related with gender and/or age of onset." (PMID 39475915, 2024).
hepatocellular carcinoma (2 papers, 2021 to 2024). A malignant tumor that arises from hepatocytes. "PGLYRP2 also acts as a biomarker for an adequate immune response against hepatocellular carcinoma and improves patient outcomes." (PMID 38806963, 2024). "Previous evidence has shown that PGLYRP2 is overexpressed in hepatocellular carcinoma (HCC) cells and can significantly strengthen the anti-tumor immune response in mice." (PMID 34461924, 2021).
neuroborreliosis (2 papers, 2025). "It is also worth noting that PGLYRP2 activity has been reported to be particularly low in cerebrospinal fluid, raising the possibility that PGBb may play a role in neuroborreliosis." (PMID 39829805, 2025).
atherosclerosis (1 paper, 2021). A disease characterized by the build-up of fatty material and calcium deposition in the arterial wall resulting in partial or complete occlusion of the arterial lumen. "A high level of PGLYRP2 induces long-term inflammation and RCT damage, thus triggering atherosclerosis and myocardial infarction." (PMID 34461924, 2021).
autism (1 paper, 2024). Persistent deficits in social interaction and communication and interaction as well as a markedly restricted repertoire of activity and interest as well as repetitive patterns of behavior. "PGLYRP2 deletion causes alterations in mice with altered microbiota, which increases the incidence of autism." (PMID 39475915, 2024).
autoimmune disease (1 paper, 2021). A disorder resulting from loss of function or tissue destruction of an organ or multiple organs, arising from humoral or cellular immune responses of the individual to their own tissue constituents. "At present, relevant studies about the role of PGLYRP2 in autoimmune diseases are scant." (PMID 34461924, 2021).
bacteremia (1 paper, 2019). "As expected, PGLYRP2-KO animals had to be sacrificed earlier than their WT counterparts, and this was due to higher bacteremia." (PMID 30837960, 2019).
chronic hepatitis B (1 paper, 2025). "Additionally, endogenous PGLYRP2 levels in the serum of healthy individuals and chronic hepatitis B patients were assessed." (PMID 39946201, 2025).
colon adenocarcinoma (1 paper, 2020). "Previously we have shown that PGLYRP2/Tag-L/PGRP-L, when overexpressed in human colon adenocarcinoma HT29 cells, impaired bacterial invasion and early intracellular growth by decreasing the viability of intraphagosomal bacteria." (PMID 33425777, 2020).
dyslipidemia (1 paper, 2021). "PGLYRP2 could be used to predict SLE activity, dyslipidemia and cardiovascular disease risks in SLE patients." (PMID 34461924, 2021). "Interestingly, this study also showed that PGLYRP2 was negatively correlated to HDL-c and Apo-A1, but positively correlated to Apo-B/A1, indicating that PGLYRP2 serves as an indicator for SLE activity and a predictor for dyslipidemia." (PMID 34461924, 2021).
inflammatory bowel disease (1 paper, 2021). A spectrum of small and large bowel inflammatory diseases of unknown etiology. "Mutation in human PGLYRP2 abolishes its amidase activity and genetic association between proteins variations in PGLYRP2 and inflammatory bowel disease have been identified." (PMID 33833993, 2021).
multiple sclerosis (1 paper, 2023). A progressive autoimmune disorder affecting the central nervous system resulting in demyelination. "Studies have shown that PGLYRP2 affects brain development, and peptidoglycans have been linked to neurological inflammation and multiple sclerosis (MS) in the past." (PMID 38106542, 2023).
pneumococcal pneumonia (1 paper, 2019). A febrile disease caused by STREPTOCOCCUS PNEUMONIAE. "Taken together, we used the PGLYRP2-KO mouse model to analyze the function of this HDM in pneumococcal pneumonia." (PMID 30837960, 2019). "Therefore, we aimed to elucidate the influences of PGLYRP2 in pneumococcal pneumonia." (PMID 30837960, 2019).
pneumonia (1 paper, 2019). An acute, acute and chronic, or chronic inflammation focally or diffusely affecting the lung parenchyma, caused by an infection in one or both of the lungs (by bacteria, viruses, fungi, or mycoplasma.). "The course of clinical apparent pneumonia was significantly different in the WT vs. PGLYRP2-KO mice (p < 0.0001)." (PMID 30837960, 2019).
Sepsis (1 paper, 2020). Sepsis is defined as life-threatening organ dysfunction caused by a dysregulated host response to infection. "AXL, CDH16, PARK7, and PGLYRP2 were significantly changed in the urine of patients suffering from sepsis-induced AKI." (PMID 32194432, 2020).
Streptococcus pneumoniae Infection (1 paper, 2019). "Own unpublished observations in C57BL/6 mice indicated, that the expression of Pglyrp2 is decreased in whole lung tissue during pneumococcal infection." (PMID 30837960, 2019).
infection (6 papers, 2016 to 2025). The state of being infected such as from the introduction of a foreign agent such as serum, vaccine, antigenic substance or organism. "In vitro infection of these primary cells with S. pneumoniae significantly induced Pglyrp2 expression in AECs by twofold and by approximately 850-fold in AMs but did not alter the expression in PMNs." (PMID 30837960, 2019). "After infection, WT and PGLYRP2-KO mice showed clinical manifestation of the infection in a mean of 2 days." (PMID 30837960, 2019). "We showed here for the first time that AECs and AMs express Pglyrp2 and that this expression is upregulated in both cell types upon infection with S. pneumoniae." (PMID 30837960, 2019). "PGLYRP2 protein has previously been identified as an innate immune effector with PG amidase activity, but immune cells are thought to make a plethora of different effector molecules, either constitutively or in response to infection." (PMID 29456081, 2018). "In conclusion, our findings affirm the pivotal role of PGLYRP2 in innate antiviral immunity, mediated through its dual regulatory effects on HBV suppression and modulation of the hepatic microenvironment during infection." (PMID 39946201, 2025). "Of the top 20 contributing proteins for each infection identified by machine learning, 6 were found to be common to both LD and WNV (APOD, C4BPB, C7, HP, ITIH3, PGLYRP2), but with varying degrees of importance in each disease." (PMID 36569838, 2022). "The first mice reached the predefined humane endpoints for euthanasia 3 days after infection and there were significant differences in the approximate survival between days 3.5 and 5 in the PGLYRP2-KO vs. WT mice, but not at the end of the experiment." (PMID 30837960, 2019).
tumor (6 papers, 2018 to 2025). "Tumor-derived PGLYRP2 is well recognized to operate as a possible biomarker for appropriate immune response to many cancers." (PMID 39475915, 2024). "All genes, except PGLYRP2, were upregulated in tumor tissues, with significant increases found for CAT (P < 0.01), CXCL1 (P < 0.05), and RAF1 (P < 0.05), which agreed with the previous results." (PMID 38806963, 2024). "It is reported that PGLYRP2 is functional in tumor development, immune response in tumor microenvironment, infectious diseases, inflammatory responses and brain development." (PMID 34461924, 2021). "Hence, tumor-derived PGLYRP2 is considered as a novel biomarker for HCC, and its potential in detecting cancer immunity and designing immunotherapies is highlighted." (PMID 34461924, 2021).
bacterial infection (3 papers, 2019 to 2024). "Last, PGLYRP2 recognizes bacterial peptidoglycan, playing a role in innate immunity by modulating the immune response to bacterial infections." (PMID 38793033, 2024). "The involvement of PGLYRP2 in bacterial infection is multifaceted." (PMID 38793033, 2024). "An involvement of PGLYRP2 in acute PMR could indicate a response to bacterial infection, highlighting its role in the acute phase of the immune response." (PMID 38793033, 2024). "In addition to its role in promoting inflammation in response to bacterial infections, PGLYRP2 has anti-inflammatory properties." (PMID 38793033, 2024). "Among them, the PGLYRP2 gene is an important gene involved in bacterial infection immune response." (PMID 31443466, 2019). "Further research into PGLYRP2 and its functions in PMR could uncover its potential as a target for therapeutic interventions in bacterial infections and inflammatory diseases, with a focus on enhancing its bactericidal activities or modulating its impact on the immune response." (PMID 38793033, 2024).
cardiovascular disease (1 paper, 2021). "Measurement of PGLYRP2 level help guide the early management of SLE and prevention of SLE-associated cardiovascular diseases." (PMID 34461924, 2021). "It is therefore believed that PGLYRP2 may be used to predict the activity of SLE and the incidence of cardiovascular disease." (PMID 34461924, 2021).
PGLYRP2 also shares sentences with these, for which no sentence is quoted: cancer (5 papers); atopic dermatitis (2); colorectal carcinoma (1); contact dermatitis (1); gastritis (1); gastrointestinal mucositis (1); glaucoma (1); glioblastoma (1); Glucose intolerance (1); intracranial hemorrhage (1); ischemic stroke (1); myocardial infarction (1); neuroblastoma (1); paraplegia (1); renal dysfunction (1); rheumatoid arthritis (1); Salmonella Infections (1); Stroke (1); systemic lupus erythematosus (1); tuberculosis (1); ulcerative colitis (1).